PCSK1 (proprotein convertase subtilisin/kexin type 1)
Diseases named in the same sentence as PCSK1 in open-access papers (continued):
Sharing a sentence is not in itself a finding about the gene and the disease.
type 2 diabetes (9 papers, 2010 to 2025). "It needs to be confirmed in a prospective study before PCSK1 polymorphisms are used to predict the risk of CAD in type 2 diabetes in the Chinese population." (PMID 24489861, 2014). "Several studies on association of PCSK1 genetic vairants with metabolic traits had been done, but no study on the association of genetic variability in PCSK1 gene with CAD risk in the population with type 2 diabetes has been reported." (PMID 24489861, 2014). "Our results, together with previous findings demonstrating elevated islet alpha cell PCSK1 transcript and GLP-1 expression in islets from donors with type 2 diabetes, point towards alpha cell adaptation." (PMID 39404844, 2024). "Of the 132 type 2 diabetes Knowledge Portal effector genes, we identified 18 (14%) as candidate effector genes for at least one phenotype, including ABCC8, KCNJ11, NKX2–2, G6PC2, PAM, HNF4A, SLC30A8, RFX6, PCSK1, and GLIS3." (PMID 37333221, 2023). "While islets of donors with type 2 diabetes do not display reduced expression of PC1/3 (also known as PCSK1) and/or CPE mRNA, one study found that palmitate treatment of islets isolated from non-diabetic deceased organ donors reduced CPE protein levels." (PMID 32894308, 2020).
glioma (8 papers, 2013 to 2025). A benign or malignant brain and spinal cord tumor that arises from glial cells (astrocytes, oligodendrocytes, ependymal cells). "In glioma, PCSK1 knockdown could switch macrophages toward an antitumor immunophenotype and induce tumor regression." (PMID 36713370, 2022).
Hypoglycemia (5 papers, 2014 to 2025). A decreased concentration of glucose in the blood. "Patients with homozygous or compound heterozygous PCSK1 variants are characterized by infancy‐onset diarrhea, development of hypothalamic–pituitary dysfunction, and postprandial hypoglycemia caused by hyperproinsulinemia." (PMID 40528426, 2025). "This hallmark, together with the additional endocrinopathies like hypoadrenalism, reactive postprandial hypoglycemia, diabetes insipidus, and the high proinsulin level, were consistent with a diagnosis of PCSK1 deficiency." (PMID 34068683, 2021). "A total of 50% of the reported PCSK1 deficiency cases represented the combination of malabsorptive diarrhea, diabetes insipidus, hypoglycemia, hypercortisolism, and adrenal insufficiency." (PMID 34068683, 2021). "Disruption of the cleavage enzyme prohormone convertase-1 (PC-1, PCSK1) also presents with ACTH insufficiency, together with hypoglycemia, malabsorptive diarrhea, obesity, and hypogonadism." (PMID 33381483, 2020).
COVID-19 (4 papers, 2021 to 2025). A disease caused by infection with severe acute respiratory syndrome coronavirus 2. "The study found that autoantigens like NXPH-1, PCSK-1, SLC2A10, and DCD correlated with markers of COVID-19 severity like D-dimers, ferritin, C-reactive protein, and lactate which can increase in severe COVID-19." (PMID 36937488, 2023).
Genetic obesity (4 papers, 2022 to 2024). "This constitutes a very meaningful finding considering the mere presence of some rare heterozygous PCSK1 missense variants has been used for diagnosing genetic obesity." (PMID 36292633, 2022). "Therefore, setmelanotide is indicated in patients with genetic obesity due to either the defect in the pro-opiomelanocortin (POMC) gene, Leptin receptors (LEPR)gene, and the proprotein convertase subtilisin/kexin type 1 (PCSK1) gene." (PMID 38715796, 2024).
hypogonadotropic hypogonadism (4 papers, 2014 to 2025). Abnormal ovarian or testicular function due to insufficient hormonal stimulation from the hypothalamic-pituitary axis. "Regarding PCSK1 deficiency, hypogonadotropic hypogonadism has been reported in 7/21 cases of PCSK1 deficiency, but in 9/21 cases hypogonadism was absent and in 5/21 it was not reported." (PMID 29880780, 2018).
colorectal cancer (3 papers, 2019 to 2023). A primary or metastatic malignant neoplasm that affects the colon or rectum. "Pcsk1 is over-expressed in breast and colorectal cancers, with poor prognoses being associated with this expression." (PMID 36765634, 2023).
hypogonadism (3 papers, 2018 to 2024). A disorder characterized by decreased function of the gonads. "Remarkably, the first case of PCSK1 deficiency reported in the literature, a woman with fertility problems among other endocrinopathies, successfully became pregnant after gonadotropin treatment, demonstrating that hypogonadism could be reversed by hormonal therapy." (PMID 29880780, 2018).
LEPR deficiency (3 papers, 2024 to 2025). "For patients aged 6 years and older with POMC deficiency, PCSK1 deficiency, LEPR deficiency, or BBS, MC4R agonists are approved which could be considered when available and reimbursed." (PMID 39929239, 2025). "The MC4R agonist, setmelanotide, should be administered in patients with POMC, PCSK1, or LEPR deficiency and BBS, and the GLP-1 receptor agonists, semaglutide and liraglutide are also novel pharmacological agents that have been FDA approved for the treatment of childhood obesity." (PMID 38397265, 2024).
Adrenal insufficiency (2 papers, 2021). Insufficient production of steroid hormones (primarily cortisol) by the adrenal glands. "A high proinsulin level, congenital diarrhea, adrenal insufficiency, and other endocrinopathies were consistent with a diagnosis of PCSK1 deficiency." (PMID 34068683, 2021).
Alström Syndrome (2 papers, 2022 to 2023). "These consequences are related to proopiomelanocortin (POMC), proprotein convertase subtilisin/kexin type 1 (PCSK1), or leptin receptor deficiency (LEPR), as well as other rare genetic diseases, including BBS and Alström syndrome." (PMID 37888071, 2023).
Anosmia (2 papers, 2017 to 2020). An inability to perceive odors. "PCSK1 and POLR3B are associated with normosmic CHH, but FGF17 mutations are associated with KS and anosmia, which implies a role during early GnRH neuron migration from the olfactory placodes as well." (PMID 31996360, 2020). "Thus, unlike neurosensory hearing loss or anosmia, metabolic defects are not typically considered as primary events in CHH, apart from syndromic CHH caused by LEP, LEPR, or PCSK1 mutations resulting in both GnRH deficiency and morbid obesity." (PMID 28754744, 2017).
Anxiety (2 papers, 2019 to 2023). Intense feelings of nervousness, tension, or panic often arise in response to interpersonal stresses. "Closest genes to this isolated SNP include a pro-protein convertase gene PCSK1 and an elongation factor gene ELL2, neither of which have been linked to anxiety in any species." (PMID 30655508, 2019).
enteropathy (2 papers, 2016 to 2020). "In five patients we detect a primary immunodeficiency or enteropathy, with clinical consequences (XIAP, CYBA, SH2D1A, PCSK1)." (PMID 32081864, 2020).
hepatocellular carcinoma (2 papers, 2020 to 2022). A malignant tumor that arises from hepatocytes. "And PCSK1 is also over expressed in pure fibrolamellar hepatocellular carcinoma as one of neuroendocrine genes." (PMID 33042807, 2020).
Hyperglycemia (2 papers, 2009 to 2022). An increased concentration of glucose in the blood. "Our data demonstrating decreased Pcsk1 levels in the yolk sac after hyperglycemia insult suggests that Pcsk1 KO mice may have an unappreciated inducible vascular phenotype." (PMID 19156209, 2009).
Hypertension (2 papers, 2022 to 2023). The presence of chronic increased pressure in the systemic arterial system. "Three PCSK1 variants (rs10515237, rs6232, rs43636321, and rs3792747) were associated with increased systolic and diastolic blood pressure and risk of hypertension in 7869 European subjects." (PMID 37761915, 2023).
Obesity syndromes (2 papers, 2022). "In contrast to some monogenic obesity syndromes, which display classical Mendelian inheritance (LEP, LEPR, POMC and PCSK1), rare heterozygous variants in HTR2C are generally not fully penetrant." (PMID 36536256, 2022).
rectal cancer (2 papers, 2020 to 2021). A primary or metastatic malignant neoplasm that affects the rectum. "Studies have shown that PCSK1 is the gene most significantly associated with poor response to concurrent chemoradiotherapy (CCRT) in rectal cancer." (PMID 33042807, 2020). "Many studies have focused on identifying genes as biomarkers associated with tumor response and survival prognosis of rectal cancer patients with pCRT, such as SERPINB5, CHD4, TCN1, VNN1, EPHA4, PCSK1, and DUOX2 genes." (PMID 33506057, 2021). "Currently, a lot of previous studies have reported that genes SERPINB5, CHD4, TCN1, VNN1, EPHA4, PCSK1, and DUOX2 as prognostic biomarkers were proven to correlate with poor tumor response and survival prognosis in patients with rectal cancer receiving pCRT." (PMID 33506057, 2021). "Therefore, overexpression of PCSK1 is one of the risks of poor CCRT response and prognosis in rectal cancer patients." (PMID 33042807, 2020).
adenoma (1 paper, 2020). A neoplasm arising from the epithelium. "Moreover, we demonstrate that protein level PCSK1N, a well described inhibitor of PCSK1-mediated processing of POMC, was significantly increased in SCA, suggesting an additional mechanism responsible for the impaired POMC processing in the silent adenomas." (PMID 33066652, 2020).
blue diaper syndrome (1 paper, 2022). Blue Diaper syndrome is a hereditary metabolic disorder characterized by hypercalcaemia with nephrocalcinosis and indicanuria. "Recently, a male infant with blue diaper syndrome with a homozygous frameshift mutation in pro-protein convertase subtilisin/kexin type 1 (PCSK1) was described." (PMID 33990852, 2022). "Notably, the boy described in this case did not have hypercalcaemia, and further genetic investigation is required to determine whether PCSK1 mutations are important in other cases of blue diaper syndrome with hypercalcaemia." (PMID 33990852, 2022).
Central hypothyroidism (1 paper, 2018). A type of hypothyroidism due to an insufficient stimulation of an otherwise normal thyroid gland. "Regarding central hypothyroidism, the prevalence in subjects with PWS cannot be clearly established and has been reported as 2.1% to 72.2%; on the other hand, more than half of the individuals with PCSK1 deficiency exhibit central hypothyroidism, similar to those presenting hypocortisolism." (PMID 29880780, 2018).
metabolic syndrome (1 paper, 2023). A cluster of metabolic risk factors for CARDIOVASCULAR DISEASES and TYPE 2 DIABETES MELLITUS. "In addition, this is the first report of an association between the G rs6235 allele of PCSK1 and metabolic syndrome based on international standards." (PMID 37761915, 2023). "In addition, the G rs6235 allele of PCSK1 was the only allele associated with metabolic syndrome in adults from northwestern Mexico, increasing 1.50 times the probability of having this metabolic disease (95% CI: 1.15–1.97; p: 3.0 × 10−3)." (PMID 37761915, 2023). "The association between the G rs6235 allele of PCSK1 and metabolic syndrome might be confounded in this population because this allelic variant increased some anthropometric components of metabolic syndrome, such as BMI, weight, waist circumference, and WHR." (PMID 37761915, 2023). "Interestingly, no previous reports have associated the G rs6235 allele of PCSK1 with metabolic syndrome, only with some components of metabolic syndrome." (PMID 37761915, 2023).
myopia (1 paper, 2024). "Retinal genes in the OcclVopen*time interaction category in myopia progression include the circadian clock genes PER2 and ARNTL and PCSK1, whose product processes prohormone and neuropeptide precursors." (PMID 39028695, 2024).
neuroendocrine tumors (1 paper, 2021). "PCSK1, encoding prohormone convertase 1, belongs to the proprotein convertase family, and its overexpression has been revealed in various subtypes of neuroendocrine tumors." (PMID 34646089, 2021).
polyendocrinopathies (1 paper, 2025). "Among congenital diarrhea and enteropathies (CODEs), proprotein convertase subtilisin/kexin type 1 (PCSK1) deficiency is a rare monogenic disorder, associated with severe neonatal diarrhea and polyendocrinopathies." (PMID 42110139, 2025).
psychosis (1 paper, 2017). "Many of these genes are implicated in psychosis and schizophrenia: PCSK1 is reported to be dysregulated." (PMID 30090857, 2017).
Spinocerebellar ataxia type 43 (1 paper, 2023). "Even the neuropeptide activator Pcsk1 and its inhibitor Pcsk1n, as well as neuropeptide inactivators like Mme (which is responsible for Spinocerebellar Ataxia type 43) and Ecel1 were upregulated." (PMID 37830614, 2023).
Wiskott-Aldrich syndrome (1 paper, 2020). Wiskott-Aldrich syndrome (WAS) is a primary immunodeficiency disease characterized by microthrombocytopenia, eczema, infections and an increased risk for autoimmune manifestations and malignancies. "To study genome editing by C-SMASh Cas9, we used the Surveyor assay to measure indel formation at two different loci, the Wiskott-Aldrich syndrome (WAS) gene and the proprotein convertase subtilisin/kexin type 1 (PCSK1) gene." (PMID 32000033, 2020).
tumor (27 papers, 2011 to 2025). "Finally, we developed a gene signature (PCSK1 and SMOC1) defining the metastatic potential of the tumor and its prognostic value was validated in a cohort of thirty G1/G2 patients underwent surgical resection." (PMID 34671197, 2021). "Survival curves showed that both PCSK1 and SMOC1 protein expression levels were significantly correlated with the recurrence, and double-positive PCSK1/SMOC1 protein expression was the more unfavorable prognostic factor than a single marker, tumor size, and tumor grade." (PMID 34671197, 2021).
cancer (23 papers, 2012 to 2025). A tumor composed of atypical neoplastic, often pleomorphic cells that invade other tissues. "For patients with six types of cancer (KIRC, LUAD, LGG, GBM, UCEC, and BLCA), those in the PCSK1 low/medium-expression group had higher survival probability than those in the high-expression group." (PMID 33299884, 2020). "PCSK1 and PCSK2 expression is largely detected in cancers with neuroendocrine features, in particular, SCLC." (PMID 23409034, 2013). "Only PCSK1’s function in cancer and immunity has not been researched." (PMID 31689990, 2019).
infection (23 papers, 2011 to 2026). The state of being infected such as from the introduction of a foreign agent such as serum, vaccine, antigenic substance or organism. "Other transcripts that we previously reported as being β-cell specific, including PCSK1 and MAFB, and GLIS3 and CASR, all decreased with infection." (PMID 32093375, 2020).
genetic disorders (11 papers, 2017 to 2025). "Its use is limited to people who have been diagnosed with one of three specific rare genetic disorders caused by proopiomelanocortin (POMC), proprotein convertase subtilisin/kexin type 1 (PCSK1), or leptin receptor (LEPR) deficiency." (PMID 36297523, 2022). "Proprotein convertase subtilisin/kexin type 1 (PCSK1) deficiency, a rare recessive congenital disorder, partially overlaps phenotypically with PWS, but both genetic disorders show clear dissimilarities as well." (PMID 29880780, 2018).
endocrine disorders (6 papers, 2014 to 2025). "One of these variants, the N309K mutation in the PCSK1 gene, appeared to be the probable cause of the CDD and endocrinopathies, given that other mutations in PCSK1 are known to cause similar symptoms, whereas the other three variants (HADHA, FBXL17 and GTF3C2) are not known to be involved in CDD." (PMID 25272002, 2014). "In addition, PCSK1-deficient patients could have systemic endocrinopathies with incomplete penetrance, such as growth hormone deficiency, hypocortisolemia, and hypothyroidism." (PMID 34068683, 2021). "Thus, it is not surprising that loss-of-function mutations in PCSK1 in humans lead to a complex set of endocrinopathies including malabsorptive diarrhea, hypogonadotropic hypogonadism, adrenal malfunction, central diabetes insipidus, and hyperphagic obesity." (PMID 35963866, 2022).
metabolic disease (5 papers, 2013 to 2026). A congenital disorder (due to inherited enzyme abnormality) or acquired (due to failure of a metabolically important organ) disorder resulting from an abnormal metabolic process. "On the other hand, the G rs6235 allele of PCSK1 showed an individual association with this metabolic disorder." (PMID 37761915, 2023).
adenocarcinoma (3 papers, 2008 to 2025). A common cancer characterized by the presence of malignant glandular cells. "It had been reported that PCSK1 plays a crucial role in the neuroendocrine system, where PCSK1 is upregulated in NEPC compared to adenocarcinoma samples." (PMID 40362754, 2025). "In total, four novel genes, including NPTX1, PCSK1, ASXL3, and TRIM9, were all significantly upregulated in NEPC compared with the adenocarcinoma samples, and these genes were all associated with the neuroactive ligand receptor interaction pathway." (PMID 34646089, 2021).
cardiovascular disease (2 papers, 2025). "PCSK1, a proprotein convertase, has been identified as a promising therapeutic target for cardiovascular diseases." (PMID 41301179, 2025).
gastrointestinal disorders (1 paper, 2024). "On the other hand, the PCSK1 gene exhibits more prevalent variants that have been linked to changes in body mass index, elevated levels of circulating proinsulin, and disruptions in glucose homeostasis, which may also contribute to gastrointestinal disorders, including IBS." (PMID 38542485, 2024).
PCSK1 also shares sentences with these, for which no sentence is quoted: melanoma (11 papers); ischemia (9); breast cancer (6); ischemic stroke (6); myocardial infarction (6); brain ischemia (5); injury (5); lung carcinoma (5); osteoarthritis (5); asthma (4); cognitive deficits (4); fibrosis (4); gastric cancer (4); leukemia (4); myeloma (4); neuroblastoma (4); osteoporosis (4); Parkinson disease (4); systemic inflammatory response syndrome (4); aneurysm (3); Coronary Artery Disease (3); diabetes insipidus (3); glaucoma (3); Hepatitis (3); Hyperinsulinemia (3); lung (3); neurodegenerative disease (3); Prader-Willi syndrome (3); renal fibrosis (3); retinal degeneration (3).
A further 128 diseases each share a sentence with PCSK1 in 3 papers or fewer.